CD4 (CD4 molecule)
Diseases named in the same sentence as CD4 in open-access papers (continued):
Sharing a sentence is not in itself a finding about the gene and the disease.
melanoma (continued). "The same distribution is observed in B16-F10 melanoma-bearing mouse models given the agonistic anti-4-1BB monoclonal antibody-monotherapy or combination therapy with anti-CD4 antibody." (PMID 27619885, 2016). "We developed a murine B16.F10 melanoma model to study the effects of collaboration between tumor-specific CD4+ T cells and B cells on tumor control." (PMID 27121060, 2016). "Radio-immunotherapy resulted in increased frequencies of CD4+ and CD8+ T cells in the melanomas (88-fold for CD4+ T cells and 60-fold for CD8+ T cells)." (PMID 27160390, 2016). "Previously, we have shown that CD4+ T cells specific for a tumor-associated self-antigen (TAA) called tyrosinase-related protein 1 (TRP-1), a melanoma differentiation antigen (MDA), can treat large established tumors by direct killing of cancerous cells." (PMID 26981246, 2016). "In one study, a neoantigen-targeted vaccine induced activation of CD4 T cells that mediated rejection of B16F10 melanoma." (PMID 27192170, 2016). "Two human studies reported that neoantigens were recognized by intratumoral CD4+ T cells in patients with epithelial cancer and melanoma." (PMID 26788324, 2016). "This preferential death mechanism has been demonstrated in the CD4+ T cells of melanoma patients with advanced disease." (PMID 27766079, 2016). "The ADORA2a and A2b were differentially expressed by the subsets whose proliferation is less inhibited by melanoma cell lines (i.e. naïve CD4+ T cells and effector CD8+ T cells) when compared to other cell subsets." (PMID 26329660, 2015). "A third observation is that the anti-proliferative effects featured by melanoma cells was different on CD4+ and CD8+ T cell subsets." (PMID 26329660, 2015). "We believe that our data suggest at least one of three possible mechanisms by which pre-mNKs suppress the rejection of established melanoma by TRP-1-specific CD4+ T cells." (PMID 26405570, 2015). "The original observations of this work are that: i) primary melanoma cell lines inhibit CD4+ and CD8+ T cell proliferation, ii) such inhibition is mediated by soluble factor(s), and iii) a key role is exerted by ADO." (PMID 26329660, 2015). "Our laboratory has developed a mouse model to study mechanisms that constrain CD4+ T cell-mediated immunity to melanoma antigens that are also self antigens, using the tyrosinase-related protein (TRP) 1-specific TCR transgenic mouse model generated previously." (PMID 25875653, 2015). "We have discovered that depletion of NK1.1+ cells enhances the rejection of established melanoma tumors by adoptively transferred TRP-1 CD4+ T cells." (PMID 26405570, 2015). "Phosphorylation of the AMPK/mTOR/p70S6K/rpS6 protein axis was also significantly lower in memory than in naïve CD4+ T cells, with reduced proliferation in the presence of melanoma cells." (PMID 26329660, 2015). "Our data suggests that NK1.1+B220+ pre-mNK cells (also known as interferon-producing killer dendritic cells; IKDCs) are an important inhibitor of the CD4+ T cell response to melanoma." (PMID 26405570, 2015). "Melanoma cells abolished the function of effector memory, central memory and reduced naïve CD4+ T cell proliferation." (PMID 26329660, 2015). "In patients with appropriate HLA genotypes, serially collected PBMCs were assessed for CD8+ and CD4+ T cell reactivity against commonly expressed melanoma epitopes restricted by HLA class I and II molecules, respectively." (PMID 26143264, 2015). "Overall, these findings support the view that the melanoma cells are characterized by a selective ability to inhibit different subsets of CD4+ and CD8+ T cells." (PMID 26329660, 2015). "Proliferation of CD4+ T cells (% of proliferating cells ± SD: 84.06 ± 20.27) was significantly inhibited in the presence of melanoma cells at 1:8 (29 ± 17.1, p = 0.0001) or 1:16 (38.9 ± 11, p = 0.0008) melanoma:CD4+ T cell ratios." (PMID 26329660, 2015).
melanoma (continued). "ACT of TRP-1-specific CD4+ T cells was able to reject established B16.F10 melanoma tumors and increase survival in IL-15−/−RAG−/− hosts relative to RAG−/− hosts without the addition of antibodies." (PMID 26405570, 2015). "In some murine tumors (melanoma and fibrosarcoma), both CD4+ and CD8+ T cells were found to be required for tumor rejection." (PMID 26604855, 2015). "A durable complete response was obtained in a patient with melanoma after infusion of NY-ESO-1 specific CD4+ cells recognizing an HLA-DP4 restricted epitope." (PMID 25949894, 2015). "CD4+ T lymphocytes proliferation (% of proliferating cells ± SD: 84.06 ± 20.27) was significantly inhibited in the presence of melanoma cells either at 1:8 (24.28 ± 7.75, p = 0.0008) or 1:16 (36.3 ± 6.89, p = 0.005) melanoma:CD4+ T cell ratios." (PMID 26329660, 2015). "By quantification of Tregs (CD4+CD25+CD127-) in the circulation of melanoma patients, we also observed an increased frequency as compared to healthy donors (p = 0.02)." (PMID 26176858, 2015). "DRibbles efficiently cross-prime antigen-specific naïve CD8+ and CD4+ T cells; and DRibbles vaccine induce an anti-tumor efficacy in different tumor models such as melanomas, lung carcinomas and breast carcinomas." (PMID 25886865, 2015). "Together, these data demonstrate that the depletion of NK1.1+ cells enhances the rejection of established melanoma by adoptively transferred TRP-1-specific CD4+ T cells." (PMID 26405570, 2015). "There are also findings in humans suggesting that this T-cell population plays a relevant role in tumor regression, as clinical efficacy has been reported after passive transfer of CD4+ T cells specific for NY-ESO-1 isolated from a melanoma tumor site." (PMID 24830315, 2014). "We also found that the frequency of CD4+FoxP3+ Tregs expressing ILT2 was higher in patients with melanoma compared to healthy donors (n = 11 and 11, respectively; P = 0.003)." (PMID 24829758, 2014). "In a model of melanoma, tumor-specific CD4+ effector T cells demonstrated exhaustion and increased 2B4 and PD-1 expression." (PMID 24796533, 2014). "For example, autologous transfer of expanded CD4+ T cells recognizing melanoma antigen NY-ESO-1 produced a complete and durable response in one patient trial." (PMID 24743024, 2014). "Another antigen recognized by CD4+ T cells in melanoma had been generated by a chromosomal rearrangement resulting in a fusion of a low density lipid receptor gene with a fucosyltransferase gene." (PMID 24860567, 2014). "More recently, we have evaluated a multi-epitope vaccine incorporating 6 melanoma helper peptides (6MHP), restricted by HLA-DR molecules, that function as epitopes for CD4+ T cells." (PMID 25126421, 2014). "For instance in melanoma, CD4+ T cells were found that recognized a tumor-specific antigen generated by a non-synonymous point mutation in the gene coding for triosephosphate isomerase." (PMID 24860567, 2014). "DCIL-15-based vaccines induced durable Type-1 (i.e. IFNγ-producing) CD8+ T cells reactive against the melanoma-associated Ag TRP2, even in CD4+ T cell-deficient mice." (PMID 25941586, 2014). "Decreased CD134 levels on CD4+ T-cells in sentinel LNs draining primary melanomas correlated with more advanced tumor features and nodal involvement." (PMID 24435119, 2014). "We detected evidence of in-vivo cross presentation of immunogenic shared melanoma tumor antigens, and stimulation of tumor antigen-specific type I, activated, CD4+ and CD8+ T cell responses at baseline that were augmented with ipilimumab therapy in the blood." (PMID 24498358, 2014). "CD4 cells have also been found to develop cytotoxic activity and be able to eradicate melanoma tumors in lymphopenic hosts." (PMID 24690990, 2014). "Our findings are concordant with a recent study showing that agonist CD137 antibody induced the expression of PD-1 on CD8+ and CD4+ TILs from mice bearing B16 melanoma when they were immunized with a cell-based vaccine." (PMID 24367702, 2013).
melanoma (continued). "Modification of the melanoma antigen, gp100, with glycans (high mannose) interacted specifically with DCs and induced enhanced CD4+ T-cell responses." (PMID 24228179, 2013). "The Dectin-2 lentivector encoding the human melanoma antigen, NY-ESO-1, stimulated CD4+ and CD8+ T cells in mice." (PMID 24228179, 2013). "In our experiment, we found elevated levels of IL-17 in melanoma tumor tissues, and small numbers of CD4+ and CD8+ T cells producing IL-17, there were much more IL-17-producing γδ T cells in tumor tissues." (PMID 24453427, 2013). "Considering the dominant Th1 profile assessed by IFN-γ production in MELOE-1 stimulated microcultures from melanoma patients, we expected to derive Th1 CD4 specific T cell clones." (PMID 23284752, 2012). "Ex vivo generated, tumor-reactive, autologous CD4+ T cell clones have successfully been used to treat melanoma patients." (PMID 23145026, 2012). "For example, CD4+ T cells specific for MAGE-A3161-175 or for MAGE-A3171-185 peptides were obtained upon in vitro stimulation of PBMCs from melanoma patients." (PMID 22797815, 2012). "Further, NK cells activated by DC treatment can elicit protective responses against melanoma challenge up to one year with helper signal from CD4+ T cells." (PMID 22457721, 2012). "In order to precisely characterize MELOE-1 specific CD4 T cells in melanoma patients, we documented the Th1 and Th2 profile of specific CD4 T cells induced after PBMC stimulation with MELOE-1 antigen." (PMID 23284752, 2012). "In this study, we documented the spontaneous recognition of two melanoma cell lines by two CD4 T cell clones specific for the central region 11–30 in the DR1 context (5F9) and the C-term region in the DQ2 context (4E2)." (PMID 23284752, 2012). "For instance, tumor-reactive CD4+ T cells were found to develop cytotoxic activity and eradicate large established melanoma after transfer into lymphopenic hosts." (PMID 23145026, 2012). "In this study, our objective was to define the ability of this promising melanoma antigen to induce CD4 specific T cells in vitro, from healthy subjects and melanoma patients." (PMID 23284752, 2012). "Immune-mediated protection against melanoma development directly correlated with the magnitude of IFN-γ responses by both NY-ESO-1-specific CD4+ T as well as CD8+ T cells." (PMID 22567144, 2012). "The MC2 and MA3 TCR were surface-expressed and mediated CD8 T-cell functions towards melanoma cell lines and CD4 T-cell functions towards dendritic cells, respectively." (PMID 22400038, 2012). "The mislocalization of DR4 and DR5 has been observed in other cell types, including CD4+ T cells and cells of cervical neoplasia, melanoma, and non-small cell lung cancer (NSCLC)." (PMID 22909995, 2012). "Recent studies indicated that tumor-reactive CD4+ T cells have a potential to up-regulate expression of MHC class-II on melanoma B16 cells, and thereby reject the cells by an MHC-II restricted mechanism in a mouse model." (PMID 23145026, 2012). "We molecularly characterized TCRαβ genes of an MC2/A2-specific CD8 and MA3/DP4-specific CD4 T-cell clone derived from melanoma patients who responded clinically to MAGE vaccination." (PMID 22400038, 2012). "Preferential CD4+ lymphopenia has been observed in melanoma patients that were treated with an extended dose of TMZ." (PMID 23133490, 2012). "We show that stimulation of melanoma patients PBMC with MELOE-1 whole antigen induces the growth of Th1 CD4 T cells specific of the various regions of the antigen in all melanoma patients but one." (PMID 23284752, 2012). "In order to formally characterize the recognized epitopes, we derived CD4 T cell clones specific for each region of MELOE-1 by limiting dilution, from microcultures of healthy donors or melanoma patients, containing at least 0.5% of specific CD4 T cells." (PMID 23284752, 2012).
melanoma (continued). "As for healthy donors, the global frequency of MELOE-1 specific CD4 T cells can be roughly estimated and ranged from 2.5×10−7 to up to 6.5×10−6 among CD4 T cells from melanoma patients." (PMID 23284752, 2012). "CD8 T-cell clone EB81-CTL16 and CD4 T-cell clone R12-C9, which were established from melanoma patients following MAGE vaccinations, were used to obtain genes encoding for MC2/A2- and MA3/DP4-specific TCRαβ's." (PMID 22400038, 2012). "We further tested the reactivity of these CD4 T cell clones against HLA-matched melanoma cell lines positive for meloe expression and expressing HLA-DQ and DR at the cell surface." (PMID 23284752, 2012). "The authors showed that ABCB5+MHC class II+ cells displayed higher capacity than ABCB5- MHC class II-negative melanoma cells to inhibit IL-2-dependent T-cell activation and support the induction of CD4+CD25+FoxP3+ regulatory T cells." (PMID 21526207, 2011). "We previously found that administration of an interleukin 2/diphtheria toxin conjugate (DAB/IL2; Denileukin Diftitox; ONTAK) to stage IV melanoma patients depleted CD4+CD25HIFoxp3+ regulatory T cells and expanded melanoma-specific CD8+ T cells." (PMID 22165955, 2011). "OVA specific CD4 T cells have also been show to enhance the expansion of cognate memory CD8 T cells recognizing melanoma-expressed OVA." (PMID 22046294, 2011). "From clinical trials in melanoma patients it has become clear that both CD4+ and CD8+ T cells are required to induce effective antitumor responses." (PMID 21892941, 2011). "This work establishes that CD4 T cell help is dispensable for the generation of protective memory T cell responses to melanoma." (PMID 22046294, 2011). "Like the CD8 T-cells, the effector CD4+ T-cells infiltrating B16 melanoma expressed much higher levels of KLRG1 and PD-1 in response to α4-1BB or combination therapy." (PMID 21559358, 2011). "By Day-25 nearly all the CD8+ T-cells and the majority of CD4+ effector T-cells infiltrating the B16 melanoma tumors of α4-1BB and α4-1BB/αCTLA-4 treated mice are KLRG1+." (PMID 21559358, 2011). "At variance with our data, previous studies have reported the isolation of ESO-specific CD4+ T cells with suppressive functions from circulating lymphocytes of patients with advanced melanoma." (PMID 21829534, 2011). "4-1BB activation promoted very strong CD8 infiltration of B16 melanoma, but in doing so depressed the relative fraction of CD4+ effector cells." (PMID 21559358, 2011). "The activation of CD8 T-cells by α4-1BB coupled with the expansion of CD4 effector T-cells by αCTLA-4 clearly accounts for some of the observed synergy between these agents in rejecting B16 melanomas." (PMID 21559358, 2011). "We recently showed spontaneous MAGE-C1/CT7-specific CD4+ T cells in the blood of patients with melanoma and MAGE-C1/CT7-specific humoral response in multiple myeloma patients." (PMID 21738656, 2011). "The present studies support the viability of anti-CD4 therapy in conjunction with surgery for melanoma patients." (PMID 22046294, 2011). "B16 melanoma expressing NP-Ep63K was inoculated into TCRmini-Foxp3GFP mice and CD4+ T cell populations were analyzed in the control and tumor-draining lymph nodes and tumors 19 days after tumor inoculation." (PMID 21049016, 2010). "Our screening approach identified new HLA-DRB1*0301-restricted CD4+ T cell epitopes derived from melanoma antigens." (PMID 21152437, 2010). "In both cases, small numbers of naïve CD4+ T cells specific to the Trp1 melanoma antigen were transferred into irradiated recipient mice bearing established B16 melanoma." (PMID 21076522, 2010). "The current report provides for the first time functional evidence of tumor reactivity of CD4+CD8+ DP Tαβ cells in human melanomas." (PMID 20052413, 2010). "Eleven of nineteen melanoma patients had CD4+ T cells responses to this epitope region (i.e., aa 37–58)." (PMID 20981248, 2010).
melanoma (continued). "Distribution of T cells subsets based on CD3, CD4, CD8 amongst melanoma patients PBMC and tumor associated lymphocytes and healthy donor PBMC." (PMID 20052413, 2010). "This epitope was mapped to aa 19–34 of SSX2 using truncated peptide assays and was recognized by CD4+ T cells from an SSX2-expressing melanoma patient." (PMID 20981248, 2010). "Interestingly, MHC class II surface expression on human melanoma cells has been described to be associated with good prognosis, suggesting that endogenous tumor antigen-specific CD4+ T cells might become activated by tumor cells and exert their anti-tumor effects directly or indirectly." (PMID 21152437, 2010). "Recently, two articles confirmed the positive contribution of CD4+ T cells in adoptive immunotherapy against melanoma, both describing a direct tumorlytic effect of these transferred T cells." (PMID 21076522, 2010). "Ramirez-Montagut and coworkers observed increased survival upon DTA-1 application in their tumor models (BALB/c mice injected with RENCA cells and C57BL/6 mice inoculated with B16 melanoma cells), which required presence of CD4+ and CD8+ T cells." (PMID 20936139, 2010). "The expression of GILT has been found to restore the processing of cysteinylated melanoma tumor Ags and CD4+ T cell recognition of tumors cells." (PMID 20016802, 2009). "Since melanoma cells express HLA class II molecules, they can act as APCs and present their own tumor Ags to CD4+ T cells." (PMID 20016802, 2009). "Long-lasting immune responses and protection against melanoma is largely dependent upon the activation of helper CD4+ and cytotoxic CD8+ T cells." (PMID 20016802, 2009). "We have demonstrated that the insertion of GILT in melanoma cells in vitro has the ability to restore CD4+ T cell recognition." (PMID 20016802, 2009). "Collectively, GILT expression can play an important role in enhancing CD4+ T cell recognition of melanoma cells." (PMID 20016802, 2009). "In this review, we discuss potential melanoma antigens (Ags) and their role in utilizing the HLA class II pathway to elicit tumor Ag-specific CD4+ T cell responses in order to effectively induce long-lasting CD8+ antitumor memory." (PMID 20016802, 2009). "We also discuss the role of endolysosomal cathepsins and Gamma-Interferon-inducible Lysosomal Thiol reductase (GILT) in Ag processing and presentation, and at enhancing CD4+ T cell recognition of melanoma cells." (PMID 20016802, 2009). "Others have observed a preferential lymphopenia in the CD4+ compartment in melanoma patients after treatment with TMZ8." (PMID 22275974, 2008). "Further, Qu Spez-educated DC stimulated CD4+T cells in a allogeneic mixed lymphocyte reaction and activated melanoma antigen Melan-A/MART-1-specific M77-80 CD8+T cells as evidenced by increased secretion of TNF-α and IFNγ." (PMID 18533025, 2008). "Depletion of these immunosuppressive Treg cells using anti-CD25 monoclonal antibodies enables a CD8+ and CD4+ T cell dependent immune rejection against the progression of melanoma in mice." (PMID 18334033, 2008). "Despite the intrinsic limitations of this study, these findings highlight the role of CD4+ T-lymphocytes in the anti-melanoma immune response." (PMID 17129373, 2006). "Approximately half of the CD4+ clones were weakly cytotoxic against the melanoma cell line used for stimulation." (PMID 16819544, 2006). "Several other studies have reported isolation of HLA class II-restricted melanoma-specific CD4+ CTLs, including clones recognising MAGE-3, NY-ESO1 and tyrosinase epitopes." (PMID 16819544, 2006). "Nevertheless, our data allow us to conclude that melanoma-reactive precursor cells exist in the peripheral blood of such donors and that the precursors of melanoma-reactive CD4+ T cells are common." (PMID 16819544, 2006). "Our report is the first to demonstrate the generation of predominantly CD4+ melanoma-reactive clones, many interferon-γ secreting, from normal donors." (PMID 16819544, 2006).